Y_RNA (Y RNA )
Gene: Miscellaneous RNA gene on chromosome 1 (55,484,871 to 55,484,972, reverse strand). Ensembl gene ENSG00000272051.
Homologues: Orthologues: chimpanzee Y_RNA (100% identical), macaque Y_RNA (93% identical). Paralogues in human: RNY3 (90% identical), Y_RNA (90% identical), Y_RNA (89% identical), Y_RNA (88% identical), RNY3P1 (87% identical), Y_RNA (87% identical), RNY3P14 (86% identical), Y_RNA (86% identical), Y_RNA (85% identical), Y_RNA (84% identical), RNY3P16 (83% identical), RNY3P5 (83% identical), and 95 more.